ENSG00000225649 (novel transcript)
Synonyms: LOC100506474
Gene: Long non-coding RNA gene on chromosome 2 (12,736,888 to 13,007,066, reverse strand). Ensembl gene ENSG00000225649.
Diseases named in the same sentence as ENSG00000225649 in open-access papers:
ENSG00000225649 is named in the same sentence as 1 disease in open-access papers, as found by Europe PMC text mining. Sharing a sentence is not in itself a finding about the gene and the disease.
ENSG00000225649 shares sentences with these, for which no sentence is quoted: cancer (1 paper).